PTPN2 (protein tyrosine phosphatase non-receptor type 2)
Diseases named in the same sentence as PTPN2 in open-access papers (continued):
Sharing a sentence is not in itself a finding about the gene and the disease.
inflammatory bowel disease (22 papers, 2010 to 2025). A spectrum of small and large bowel inflammatory diseases of unknown etiology. "GWAS revealed that loss-of-function mutations in PTPN2 were associated with increased intestinal permeability, which is an early etiological event of chronic immune diseases, such as inflammatory bowel disease and celiac disease." (PMID 41019340, 2025). "Finally, we demonstrate how an inflammatory bowel disease (IBD) risk allele increases the usage of a lowly-used isoform of PTPN2, a negative regulator of inflammation." (PMID 40866368, 2025). "To demonstrate how low-usage sQTLs can dysregulate alternative splicing and predispose to IMDs, we further investigated a PTPN2 sQTL that implicates a lowly-used intron that colocalised with an inflammatory bowel disease (IBD) associated risk locus at 18p11.21." (PMID 40866368, 2025). "Recent research has investigated the effect of treating human intestinal epithelial cells with the PTPN2:rs1893217-G SNP that is a risk factor for inflammatory bowel disease (IBD) with different polyamines." (PMID 34445589, 2021). "At the RNA and protein levels, PTPN2 mRNA and protein expression levels are elevated within the epithelial cells in inflammatory bowel disease (IBD)." (PMID 36077422, 2022). "The protein tyrosine phosphatase nonreceptor 2 (PTPN2) gene risk variant rs1893217 is associated with gut dysbiosis in inflammatory bowel disease (IBD), and PTPN2 was mentioned as a possible risk gene for PSC." (PMID 34442830, 2021). "PTPN2 has been known as a negative regulator of inflammatory signaling in the interferon gamma (IFN-γ)-treated THP-1 cells or inflammatory bowel disease." (PMID 27611995, 2016). "Indeed, the pathogenesis of inflammatory bowel disease is complex, potentially involving not only AIEC, but human susceptibility genes including a loss of function variant of the protein tyrosine phosphatase non-receptor type 2 (PTPN2) gene." (PMID 36865539, 2023). "Loss of activity of the inflammatory bowel disease (IBD) susceptibility gene, protein tyrosine phosphatase non-receptor type 2 (PTPN2), is associated with altered microbiome composition in both human subjects and mice." (PMID 40955058, 2025). "Genome-wide association studies identified PTPN2 (protein tyrosine phosphatase, non-receptor type 2) as susceptibility gene for inflammatory bowel diseases (IBD)." (PMID 22457781, 2012). "Protein tyrosine phosphatase nonreceptor type 2 (PTPN2) plays a critical role in the pathogenesis of inflammatory bowel diseases (IBD)." (PMID 34201918, 2021). "A dysfunction of protein tyrosine phosphatase nonreceptor 2 (PTPN2), caused by the single nucleotide polymorphism (SNP) rs1893217, is associated with intestinal dysbiosis and a more severe disease course in inflammatory bowel disease (IBD) patients." (PMID 34442830, 2021).
diabetes (20 papers, 2011 to 2025). "When studying interactions with diabetes, we observed that the eQTLs of PTPN2 located at 18p11.21 modified the association between diabetes and CRC risk (pinteraction = 2.31 × 10−5)." (PMID 32207560, 2020). "These previous studies reported that the expression of TRIM4 and PYGL in colon transverse tissue was associated with colorectal cancer risk, while PTPN2 expression in colon transverse tissue modified the association of diabetes with colorectal cancer risk." (PMID 33142733, 2020). "In summary, by incorporating functional information and conducting aggregated gene‐based testing, the most significant interactions we observed where between FOXA1 and BMI among men, and between PTPN2 and diabetes for CRC risk." (PMID 32207560, 2020). "The strongest association was for FOXA1 and BMI with CRC risk for men, and the predicted gene expression level of PTPN2 interacted with diabetes on CRC risk among men and women combined." (PMID 32207560, 2020). "Tyrosine‐protein phosphatase non‐receptor type 2 (PTPN2) is an important protection factor for diabetes and periodontitis, but the underlying mechanism remains elusive." (PMID 31373168, 2019). "Recently, the Diabetes Autoimmunity Study in the Young (DAISY) reported an interaction between a PTPN2 variant PTPN2 rs1893217 and a functional VDR variant VDR rs2228570 which is associated with progression of T1DM." (PMID 30246029, 2018). "As described in Sections 3.1.3 and 3.1.1.7, diabetes-related GLIS deficiency leads to preferential upregulation of the BimS isoform, and diabetes-related PTPN2 deficiency leads to increased activation of STAT-1 resulting in increased Bim transcription." (PMID 26405162, 2015). "Consequently, mutations in the PTPN2 gene frequently lead to the development of inflammatory disorders such as Crohn’s disease, hepatitis, diabetes, and atherosclerosis." (PMID 41019340, 2025). "Since diabetes is also an inflammation‐related disorder, it might suggest a mechanism on how PTPN2 interacts with diabetes on CRC risk." (PMID 32207560, 2020). "Furthermore, increased inflammasome activation upon loss of PTPN2 might also contribute to the increased disease risk for RA and diabetes observed in PTPN2-variant carriers." (PMID 32751912, 2020). "Although abundant data is demonstrating that PTPN2 alleviates insulin resistance in diabetic mice, some studies have shown a conflicting result that activation of PTPN2 inhibits insulin signaling, thereby exacerbating the development of diabetes." (PMID 37670950, 2023). "Variants in the gene locus encoding PTPN2 are associated with several inflammatory disorders, including IBD, RA, and diabetes, highlighting the important anti-inflammatory function of PTPN2." (PMID 32751912, 2020). "Meanwhile, liver lesions induced by diabetes such as hepatic vacuolization, necrosis and fibrosis were significantly improved after PTPN2 gene transfer, as indicated by pathological examination." (PMID 30955247, 2019). "We found PTPN2 expression was suppressed in kidney of diabetic mice and correlated with renal injury in diabetes." (PMID 30955247, 2019). "In summary, these results indicated that PTPN2 gene therapy effectively prevented diabetes‐induced renal inflammation in DN." (PMID 30955247, 2019). "As we have learned, some of the diabetes susceptibility genes e.g., GLIS3, PTPN2, BACH2 and Cathepsin H, regulate Bim expression." (PMID 26405162, 2015). "Additionally, it was reported that SNPs in PTPN2 rs2542151 in patients with MASLD was associated with higher severity of fatty liver disease and a higher prevalence of type 2 diabetes mellitus (T2DM)." (PMID 41019340, 2025). "Therefore, deletion of PTPN2 often leads to the development of inflammation-related diseases such as Crohn’s disease, hepatitis, diabetes, and atherosclerosis." (PMID 37670950, 2023).
diabetes (continued). "The PTPN2 gene, which encodes the T-cell protein tyrosine phosphatase (TCPTP), may partially explain the increased risk for CRC neoplasia due to diabetes." (PMID 35736432, 2022). "We identified an interaction between PTPN2 (protein tyrosine phosphatase nonreceptor‐type 2) and diabetes with CRC risk." (PMID 32207560, 2020). "At present, there are many reports of PTPN2-knockout mouse model to study diabetes." (PMID 30246029, 2018). "Thus, we then explored whether liver lesions induced by diabetes were improved after PTPN2 overexpression." (PMID 30955247, 2019). "However, the downstream mediator of PTPN2 in modulating micro‐inflammation during diabetes remains unknown." (PMID 30955247, 2019).
celiac disease (16 papers, 2011 to 2025). An autoimmune genetic disorder with an unknown pattern of inheritance that primarily affects the digestive tract. "Within the PTPN2 coding region, studies have demonstrated additional association findings with RA and celiac disease." (PMID 28791018, 2017). "So far, PTPN2 has been shown to be a susceptibility gene for celiac disease and for diabetes modifying beta-cell responses to viral RNA and apoptosis." (PMID 22457781, 2012). "Researchers have been studied that IBD and celiac disease have the similar genetic background; IL18RAP, PTPN2, TAGAP, and PUS10 have been identified as shared risk loci for both CD and celiac disease." (PMID 36204317, 2022). "This particular variant is considered a risk variant for T1D and celiac disease, and correlated with impaired IL-2 signalling in CD4+ T cells as measured by decreased phosphorylation of STAT5 (pSTAT5) but also reduced PTPN2 expression." (PMID 33193091, 2020). "Conversely, previous reports of an overlap in association between T1D and celiac disease were in regions encoding genes highly expressed in T lymphocytes (RGS1, PTPN2 and CTLA4 in celiac; PTPN2 and CTLA4 in T1D)." (PMID 21852963, 2011).
melanoma (15 papers, 2018 to 2025). A malignant, usually aggressive tumor composed of atypical, neoplastic melanocytes. "PTPN2 variants remained mostly to be shallow deletions, while the peak of mutation count appeared at the endometrial cancer and melanoma." (PMID 37884566, 2023). "Our work in the current study was focused on melanoma and colorectal cancer; however, Ptpn2 has been implicated as an important regulator of a variety of cancers." (PMID 36968224, 2023). "High expression of miR-155 or low expression of its target, PTPN2, was associated with higher survival of melanoma patients." (PMID 34827646, 2021). "Furthermore, an elegant recent report showed that CSDE1 promotes immune escape in melanoma by stabilizing the levels of PTPN2 mRNA, which encodes the STAT1 phosphatase TCPTP." (PMID 38600987, 2024). "In order to dissect the mechanism by which PTPN2 acts as an oncogene in melanoma and how its loss correlates with increased sensitivity of tumor cells to immunotherapy, it is important to underline that the tyrosine phosphatase inhibits IFNγ signaling by dephosphorylating STAT1 and JAK1." (PMID 33003469, 2020). "Loss of PTPN2 also sensitized tumors to immunotherapy in models of melanoma and colon cancers." (PMID 29764444, 2018). "In vivo, PTPN2 inhibitor cotreatment significantly reduced melanoma and colorectal tumor growth and enhanced mouse survival compared with anti-PD-1 treatment alone, and this was accompanied by increased tumor infiltration by granzyme B+ CD8+ T cells." (PMID 36968224, 2023). "We examined the effect of the PTPN2 inhibitors on the IFNγ signaling response of mouse melanoma and colon cancer cell lines in vitro by comparing the effectiveness of the PTPN2 inhibitors with results of CRISPR/Cas9-mediated Ptpn2 deletion." (PMID 36968224, 2023). "Previous work demonstrated that Ptpn2 silencing in B16F10 melanoma cells sensitized them to anti-PD-1 therapy in vivo by increasing IFNγ-induced antigen presentation and T-cell activation, culminating in inhibition of tumor growth." (PMID 36968224, 2023). "In an in vivo study using CRISPR-Cas9 in transplanted B16 melanoma tumors in mice, Ptpn2 deletion in cancer cells has been shown to improve tumor response to immunotherapy, including an anti-PD-1 antibody and a tumor cell vaccine (GVAX)." (PMID 38022587, 2023). "To this end, we generated control and Ptpn2 knockout B16F10 murine melanoma cell line by CRISPR/Cas9 editing." (PMID 36968224, 2023). "As was observed for melanoma cells, IFNγ treatment of Ptpn2 knockout CT26 and MC38 cells enhanced the expression of the IFNγ response genes Cxcl1, Ccl5, Stat1, Stat2, Stat3, Irf1, Pd-l1, Tap1, and Casp8, compared with IFNγ-treated control cells." (PMID 36968224, 2023). "Ptpn2 knockdown likely increases melanoma cell sensitivity to IFNγ by enhancing STAT1, STAT3, and STAT5 phosphorylation and MHC-I, MHC-II, and PD-L1 expression." (PMID 38022587, 2023). "A CRISPR-Cas9 screen identified PTPN2 deletion to enhance response to anti-PD-1 immunotherapy in a murine tumor model with B16 melanoma cells." (PMID 35911672, 2022). "Here, immunotherapy based on the Ptpn2 gene was combined with DOX chemotherapy for the treatment of malignant melanoma." (PMID 35233535, 2022). "Having established that Ptpn2 gene knockout sensitizes melanoma cells to IFNγ treatment, we next asked whether the small-molecule Ptpn2 inhibitors (PTP 1 through PTP 10) could have the same effect." (PMID 36968224, 2023). "The development of small-molecule PTPN2 inhibitors such as those described here will enable further study of the mechanism by which PTPN2 inhibition sensitizes resistant tumors to immunotherapy beyond melanoma and colorectal cancer." (PMID 36968224, 2023). "Based on studies with B16 melanoma cells, which typically show resistance to PD-1 therapy, adding a PTPN2 inhibitor to anti-PD-1 regimens may help expand the pool of cancer patients responsive to checkpoint inhibition." (PMID 35911672, 2022).
melanoma (continued). "Specifically, loss-of-function of PTPN2 sensitized B16 cells to immunotherapy in vivo and increased the sensitivity to T cell immunity in a Braf/Pten melanoma model, without affecting cell viability and growth in the absence of T cells." (PMID 33003469, 2020). "Thus, inhibition of Ptpn2 by the small-molecule PTP 9 sensitizes melanoma tumors to anti-PD-1 therapy in vivo, at least in part, by restoring the ability to respond to IFNγ, thereby increasing T-cell chemokine expression and recruitment of cytolytic T cells to the tumor microenvironment." (PMID 36968224, 2023). "Thus, reducing the expression of Ptpn2 may provide a new scheme for the target immunotherapy of melanoma." (PMID 35233535, 2022). "Deletion of protein tyrosine phosphatase non-receptor type 2 (Ptpn2), a regulator of growth factor and cytokine signaling pathways, has been shown to sensitize murine B16F10 melanoma cells to IFNγ and anti-PD-1 immunotherapy." (PMID 36968224, 2023). "Since PTPN2 is a negative regulator of JAK/STAT signaling, inhibiting PTPN2 predictably increases responses to anti-PD-L1 therapy in murine melanoma YUMM1.1 cells in vitro and in vivo." (PMID 35911672, 2022). "In a mouse model of melanoma, an in vivo CRISPR screen identified novel immunotherapy targets, including PTPN2 and SOCS1, both of which act to decrease IFN signaling." (PMID 31133614, 2019). "Deletion of protein tyrosine phosphatase nonreceptor type 2 (PTPN2) increased the efficacy of ICIs in melanoma cells, as PTPN2 diminished the IFN-γ-mediated effects on antigen presentation and suppression of tumor growth." (PMID 40108693, 2025). "Similarly, to promote melanoma cell aggressiveness CSDE1 downregulates the levels of PTEN mRNA, while it upregulates the levels of PTPN2 and PMEPA1 mRNAs." (PMID 38600987, 2024). "For example, the protein tyrosine phosphatase nonreceptor type 2 (Ptpn2) is highly expressed in melanoma and can reduce anti-tumor immunity by reducing the frequency of progenitor T cells maturing to killer T cells and interfering with killer T cells responding to IFN-γ signals." (PMID 35233535, 2022). "Therefore Ptpn2 has recently been identified as a novel cancer immunotherapy target in a CRISPR screening in vivo, where deletion of this gene increased the efficacy of immune checkpoint blockade therapy in melanoma." (PMID 33122197, 2020). "This may be related to the different tumor microenvironments of melanoma and AML, suggesting that PTPN2 may not act as a therapeutic target in all hematologic tumors, but its role in AML is indispensable." (PMID 37884566, 2023). "Notably, deletion of protein tyrosine phosphatase nonreceptor type 2 (PTPN2), a negative modulator of STAT1/JAK1 signaling, enhanced the efficiency of immunotherapy in melanoma tumors by increasing the activation of CD8+ T cells and the IFN-γ signaling pathway." (PMID 34827646, 2021).
glioma (11 papers, 2012 to 2025). A benign or malignant brain and spinal cord tumor that arises from glial cells (astrocytes, oligodendrocytes, ependymal cells). "It was also shown that PTPN2 expression levels are strongly associated with prognosis in patients with glioma and glioblastoma." (PMID 33122197, 2020). "Clinically, higher levels of PTPN2 were associated with a worse overall survival both in patients with gliomas and glioblastomas." (PMID 29764444, 2018). "There was a strong association between higher PTPN2 expression and shorter OS in patients with glioma." (PMID 29764444, 2018). "PTPN2 expression level was increased in glioblastomas and associated with gliomas of the IDH wild-type and mesenchymal subtype." (PMID 29764444, 2018). "Next, we conducted a comprehensive analysis of the biological functions associated with PTPN2 in glioma." (PMID 29764444, 2018). "Similar to previous studies, PTPN2 expression was strongly linked with immune responses in glioma." (PMID 29764444, 2018). "In the multivariate analysis aimed to prove the independent prognostic value of PTPN2, a higher PTPN2 expression was still an independent prognostic factor in patients with glioma, after adjustment of clinical factors (age, IDH mutation status, and tumor grade)." (PMID 29764444, 2018). "Nevertheless, HOXA5, PTPN2, WT1, HOXD10, POSTN, ADAMDEC1 and MYBPH were overexpressed in ATRX-mt glioma tissues with high-risk scores compared with low-risk scores." (PMID 37812190, 2023). "In glioma tissues from the high-risk group of the training cohort, HOXA5, PTPN2, WT1, HOXD10, POSTN, ADAMDEC1 and MYBPH were highly expressed." (PMID 37812190, 2023). "In the test cohort, HOXA5, PTPN2, WT1, HOXD10, POSTN, ADAMDEC1 and MYBPH levels were elevated in glioma tissues with high-risk scores." (PMID 37812190, 2023). "Wu and colleagues examined glioma patient datasets from The Cancer Genome Atlas and showed that PTPN2 mRNA levels are upregulated in parallel with advancing tumor grade." (PMID 36968224, 2023). "Up-regulation of PTPN2 expression induced by inflammatory response and oxidative stress contributes to glioma progression." (PMID 35957898, 2022). "PTPN2 contributes to glioma progression either via inflammation cytokines interferon-γ and TNF-α, or oxidative stress." (PMID 36077422, 2022). "PTPN2 levels are high in some gliomas, laryngocarcinoma, and thyroid cancer, with high PTPN2 levels in cancer cells under oxidative stress and inflammatory conditions." (PMID 35911672, 2022). "Similar expression patterns were also reported for other immune checkpoints such as PD-L1, B7-H3, TIM-3, CD155, and PTPN2 in glioma." (PMID 31911758, 2020). "The RNA-seq data of glioma from CGGA and TCGA databases were extracted to analyze the expression pattern of PTPN2 in gliomas." (PMID 29764444, 2018). "The transcript levels of PTPN2 were significantly elevated in wild-type IDH grade II–III gliomas (Student’s t test, p = 0.003)." (PMID 29764444, 2018). "A comprehensive biological analysis was conducted, which indicated a crucial role of PTPN2 in the immune and inflammation responses in gliomas." (PMID 29764444, 2018). "Here, we investigated the relationship between PTPN2 mRNA levels and clinical characteristics in gliomas." (PMID 29764444, 2018). "PTPN2 transcript levels increased significantly with higher grades of glioma and in isocitrate dehydrogenase (IDH) wild-type and mesenchymal subtype gliomas." (PMID 29764444, 2018). "In conclusion, to the best of our knowledge, our study is the first to characterize PTPN2 expression levels in gliomas." (PMID 29764444, 2018). "We further investigated the function of 312 genes that overlapped the two gene sets using GO analysis and found similar results, which suggests a more reliable relationship between PTPN2 and inflammatory response/immune response in glioma." (PMID 29764444, 2018).